EP300 (EP300 lysine acetyltransferase)
Diseases named in the same sentence as EP300 in open-access papers (continued):
Sharing a sentence is not in itself a finding about the gene and the disease.
cancer (continued). "However, since the RIP-seq results were also validated with real-time RT-PCR, at least six genes related to “Pathways in cancer,” i.e., TGFB2, CREBBP, EP300, FOS, JUN, and MYC were certainly affected by the hnRNPM-AS1-S interaction." (PMID 37671887, 2023). "The lack of upregulation of the basal subtype genes in EP300-mutant cancers suggests this represents a distinct subclass of the basal-like/squamous subtype." (PMID 35536676, 2022). "Chromosome translocations of both EP300 and CREBBP in cancer have also been observed." (PMID 34201346, 2021). "Unlike PD-L1 negative regulators (HDAC1, HDAC2, and HDAC3), the expression ranks of PD-L1 and its positive regulators (EP300, CREBBP, IRF-1, and BRD4) negatively correlated to Grade Group in another study, suggesting an increase of function during cancer progression." (PMID 34830196, 2021). "To gather information about p300 and CBP in human cancer, we examined The Cancer Genome Atlas (TCGA) dataset and found significant correlations between EP300 or CBP mRNAs and genes identified by our integrative RNA-seq and ATAC-seq analyses, including RELA, STAT1, NFKB1, IFNGR2, and NLRC5." (PMID 33602823, 2021). "Nevertheless, it is not clear how the increase in the KAT activity of EP300 or CREBBP promotes malignant tumors." (PMID 33117683, 2020). "Our data are consistent with exposure to high glucose of gastrointestinal cancer cells, but not healthy or other cancer types, promoting a switch of a limited EP300 pool from nuclear receptors towards β-catenin leading to a pro-proliferative outcome." (PMID 32603375, 2020). "Collectively, the results indicate that in gastrointestinal, but not in multiple other cancer cell types, glucose levels selectively increase EP300 but not CBP." (PMID 32603375, 2020). "Moreover, it was elucidated that EP300 upregulation mitigated EOC cell growth and stemness, indicating it served an anti-cancer part in EOC." (PMID 32943995, 2020). "Interestingly, we found 23 genes whose expression were significantly altered by SV (P<0.05, unpaired t-test) and among them were well-known cancer-related genes CDKN2A (SV in 5 samples), PRKCA (SV in 3 samples) and EP300 (SV in 3 samples)." (PMID 28548104, 2017). "In several cancer cell lines, such as HeLa, HepG and SkNSHRA, genes downregulated by lncRNA625 knockdown were enriched for the endogenous EP300 occupancy pattern, but not enriched in hESC." (PMID 28194033, 2017). "Given the importance of these genes in cancer development, CBP/EP300 bromodomain inhibition may represent an important therapeutic strategy to reprogram oncogenic signaling pathways in human malignancies." (PMID 26731516, 2016). "Genetic studies in mice and surveys of human cancer mutations and translocations have implicated CBP/EP300 in cancer, but the role of the bromodomain in the normal and pathological function of CBP/EP300 has not been extensively studied." (PMID 26731516, 2016). "Genetic studies in mice and analysis of human cancer mutations and translocations have implicated CBP/EP300 in cancer, but the role of the bromodomain in the normal and pathological function of CBP/EP300 has not been extensively studied." (PMID 27903272, 2016). "Given the current lack of strategies to treat EP300-mutant cancers such as Adult T-cell Leukemia Lymphoma, this study paves the way towards uncovering new therapeutic venues based on our identification of novel molecular pathways dysregulated primarily in the absence of EP300." (PMID 41354653, 2025). "Thus, simultaneous suppression of CREBBP and EP300, but not that of either alone, causes synthetic lethality in SMARCA4/SMARCA2-deficient and SS18–SSX fusion cancers." (PMID 39625239, 2025). "Thus, simultaneous dual suppression of CREBBP and EP300, but not single suppression, causes synthetic lethality in SMARCB1-deficient cancers." (PMID 38839769, 2024).
cancer (continued). "Conversely, perturbations that may promote aberrant stem cell-like activity and impair differentiation (cancer-promoting genes) included bromodomain-containing proteins (BRD1, BRD2), histone acetyltransferases (EP300), and histone lysine methyltransferases (KMT2C, NSD1, SETD1B)." (PMID 38472198, 2024). "However, in EP300, high transcriptional activities rather than genomic lesions were contributing to tumor progression at pan-cancer level." (PMID 37876590, 2023). "Four CRs (TRRAP, EP300, NSD2 and MSH6) having synthetic lethal interactions with MAP2 were integrated as a MAP2 CSL module in COAD, where MAP2 was affected by two taxnes (Paclitaxel and Docetaxel).These four CRs play roles in cell cycle, notch signaling pathway and mismatch repair in human cancers." (PMID 36180906, 2022). "Moreover, the ROS/AMPK/EP300/β-catenin axis was active in human cancers and inactive in adjacent nontumor tissue, consistent with the in vivo data from mice." (PMID 32603375, 2020). "However, to our best knowledge, the cancer recurrent interaction relationship between EP300 and miR-22-5p has not been previously elucidated." (PMID 25403569, 2014). "When grouping cancer genes into canonical cancer pathways, mutations in the SWI–SNF complex (for example, SMARCA4, ARID1B and SMARCB1) and certain members of the NOTCH signalling pathway (for example, EP300 and NCOR1) were under significant subclonal, but not truncal, selection in LUAD." (PMID 37046096, 2023).
tumor (516 papers, 2005 to 2026). "N1-acetyl-L-histidine, which is released into the extracellular microenvironment in the hepatocellular carcinoma, is selectively endocytosed by tumour-associated macrophages and directly triggers the acetyltransferase EP300 by allosteric modulation." (PMID 41562074, 2025). "Taken together, our results establish coding mutations in CREBBP and EP300 as functionally and clinically relevant alterations linked to genomic instability and enhanced tumor immunogenicity." (PMID 41301688, 2025). "At relapse, emerging subclonal mutations affected key genes associated with SCLC biology, and tumours harbouring clonal CREBBP/EP300 alterations underwent genome duplications." (PMID 38480884, 2024). "APC (p = 1.7e-20), BCL9 (p = 0.0006), CREBBP (p = 8.5e−5), FLCN (p = 1.39e−7), NSD2 (p = 0.002), and EP300 (p = 1.42e−6) all had significantly higher mutation rates in MSLN low expressing tumor samples compared to MSLN high expressing tumor samples." (PMID 39174744, 2024). "CBP/EP300-BRD inhibition redirects tumour-associated MDSCs from a suppressive to an inflammatory phenotype through STAT pathway-related gene downregulation and ARG1 and iNOS inhibition, thus limiting tumour growth in a model of colon carcinoma." (PMID 36161514, 2023). "CREBBP/EP300 mutations lead to loss of MHCII expression in tumor cells and subsequently promote the development and progression of hematologic malignancies by facilitating immune escape." (PMID 36831561, 2023). "In DLBCL, CREBBP/EP300 mutations promote tumor-associated macrophage M2 polarization, thereby facilitating tumor progression in vivo and in vitro." (PMID 36831561, 2023). "Immunostaining for total and AcH3 showed fewer AcH3-positive tumor cells with EP300-knockdown, and quantitation revealed that this reduction was significant in radiated, EP300-deficient tumors." (PMID 36261421, 2022). "Regarding HATs, a recent study has shown that CREBBP/EP300 mutations contributed to both tumor progression and an aberrant TME in DLBCL." (PMID 35326620, 2022). "Mutation of EP300 differs from downstream Wnt pathway mutations that constitutively activate β-catenin signaling because p300 loss confers resistance by mediating Wnt/β-catenin–independent tumor growth." (PMID 35536676, 2022). "Further, some studies claimed that macrophage polarization in DLBCL was associated with CREBBP/EP300 mutations and in turn promotes tumor progression." (PMID 36072582, 2022). "Taken together, these findings suggest that EP300 mutations acquired during tumor evolution cause both nonsense-mediated mRNA decay and the loss of functional p300 protein in the resistant cell lines." (PMID 35536676, 2022). "For this purpose, the authors performed a genomic analysis in a cohort of DLBCL patients, in which it was shown that CREBBP/EP300 mutations were associated with tumor progression." (PMID 35326620, 2022). "Both loss- and gain-of-function mutations in the human EP300 locus were described to enhance tumor progression, suggesting context-dependent tumor-suppressive or oncogenic functions." (PMID 34465885, 2022). "The downregulation of EP300 gene expression was associated with higher anti-tumor immunity in most solid malignancies." (PMID 35664766, 2022). "Meanwhile, underlying mechanisms of CREBBP/EP300 mutations on TAM polarization within the tumor microenvironment were studied both in vitro and in vivo." (PMID 33431788, 2021).
tumor (continued). "In BC, the EP300 mutations are associated with a higher burden of tumor mutations and indicate a good clinical prognosis." (PMID 34354750, 2021). "There are both suppressor genes and tumor oncogenes mutated in all nine/nine parts of the tumor, such as EP300 and NCOR2 (NOTCH), PTEN (PI3K), EGFR (RTK-RAS) and FAT1 (Hippo)." (PMID 33922652, 2021). "There are mutated tumor suppressor genes in all (nine/nine) tumor portions, such as EP300 and PTEN in GB01, NCOR2 in GB02, and FAT1 in GB03." (PMID 33922652, 2021). "Single-cell RNA sequencing further confirmed that the presence of increased macrophages in tumor microenvironment was related to CREBBP/EP300 mutations." (PMID 33431788, 2021). "In this study, we performed the genomic analysis in a large cohort of DLBCL patients and showed that CREBBP/EP300 mutations were significantly associated with tumor progression." (PMID 33431788, 2021). "The mutations observed in CREBBP and EP300 were largely mutually exclusive, suggesting a shared tumor suppressor function between these functional paralogs." (PMID 31827074, 2019). "Immunohistochemical analysis showed that EP300 expression was significantly higher in ESCC tumor tissues, and the expression levels were associated with poor survival of ESCC patients." (PMID 31632486, 2019). "It is worth noting that HGG8 harboring mutant EP300 was a midline tumor, a location where H3K27M mutations known to affect H3K27 acetylation usually account for the vast majority of driver mutations." (PMID 29084603, 2017). "EP300 somatic mutations coupled with the deletion of the second allele were reported in different primary tumours and cell lines." (PMID 16638127, 2006). "Mutation of EP300 mediates Wnt/β-catenin–independent tumor growth." (PMID 37612583, 2024). "EP300 encodes the histone acetyltransferase p300, which is a tumor suppressor." (PMID 37612583, 2024). "Tumor mutations in CREBBP/EP300 and CASP8 were significantly associated with Th2 infiltration." (PMID 38672668, 2024). "Furthermore, CREBBP and EP300 mutations are often mutually exclusive in DLBCLs, correlating with tumor recurrence and inferior clinical outcomes." (PMID 35773729, 2022). "EP300 mutations contribute to an unfavorable phenotype in a number of solid tumors and hematological malignancies, and therefore EP300 is often considered as a tumor suppressor." (PMID 35664766, 2022). "In addition, based on Gene Set Enrichment Analysis (GSEA) and CIBERSORT algorithm, they observed that the EP300 mutation up-regulated the signal pathway of the immune system and enhanced the anti-tumor immune response." (PMID 35174173, 2021). "We suggest that CBP/EP300 loss promotes tumor growth by enabling immune evasion." (PMID 33602823, 2021). "The importance of CREBBP and EP300 mutation is underscored following analysis of tumor tissues in several cohorts of patients with SCC of the head and neck, lung, or cervix treated with radiation therapy, identifying these mutations as associated with radioresistance and poor outcome." (PMID 34732714, 2021). "Mutations in EP300 have been identified in multiple tumor types including UC (COSMIC database)." (PMID 31010895, 2019). "Furthermore, we explored the correlation between mutation and expression of EP300 and tumor progression and metastasis, as well as its prognostic value for patients with ESCC." (PMID 31632486, 2019). "Studies of truncating EP300 mutations suggested that it functioned as a tumor suppressor." (PMID 31010895, 2019). "Mechanistically, these mutations tend to disrupt the original protein function, exemplified by the disrupted substrate binding in CREBBP and EP300, or to prevent the activation of a tumor suppressor, exemplified by mutations within the SMAD4 interface or CHEK2 activation loop (Dataset EV5)." (PMID 29572294, 2018).
tumor (continued). "Among the genes influenced by EP treatment, EP300 is widely expressed and regulates several essential biological processes, including proliferation and differentiation, through its paralogous domains, with mutations in EP300 known to accelerate tumor development in SCLC mouse models." (PMID 38957470, 2024). "So, we speculate that mutations of EP300 might promote the tumor progression of MM." (PMID 35870987, 2022). "Furthermore, EP300 encodes the histone acetyltransferase paralogue p300 that manipulates different cellular processes (e.g., proliferation, apoptosis, and DNA repair) and promotes tumor growth through its downstream oncogene target MITF." (PMID 36125617, 2022). "Increased EP300 expression was detected in HBV‐positive tumor tissues and cells compared to their control counterparts." (PMID 40095759, 2025). "Using Tumor Immune Estimation Resource (TIMER) data, we found patients with CREBBP, EP300, CHD7 mutations and PRDM9 amplifications associated with low B‐cell infiltration, potentially aiding tumor growth." (PMID 40693457, 2025). "Additional driver alterations are necessary for the appearance of a tumor and 90% of patients with FL have certain mutations in genes regulating transcription and chromatin remodeling such as CREBBP, EP300, KMT2D and EZH2." (PMID 40725159, 2025). "The levels of genes associated with tumor metastasis, including MAPK1, MAPK14, COL5A1, FN1, EP300, and FOSL2, were significantly downregulated after SH intervention." (PMID 41444284, 2025). "The chromatin remodelling factor BRG1 forms a BRG1-EP300 complex with the histone acetyltransferase EP300, driving the expression of proliferation-related genes and affecting tumour progression." (PMID 40665344, 2025). "The tumor suppressor LRP1B, known to correlate with high tumor mutational burden and increased neoantigen load, was frequently co-mutated with KMT2C and EP300, particularly in UTUC, where both LRP1B and chromatin remodeling genes are recurrently altered." (PMID 41395625, 2025). "Our analysis showed that EP300, which encodes the histone acetyltransferase p300, was significantly upregulated on RMC tumor cells after treatment with ICT." (PMID 41290625, 2025). "Inactivation of CREBBP and EP300 is considered a therapeutic strategy to achieve tumor radiosensitization due to impaired homologous recombination repair." (PMID 41301688, 2025). "We correlated epiRG scores with six major immune cell types and observed certain epiRG scores (CHD7‐mut, CREBBP‐mut, EP300‐mut) positively correlated with tumor proliferation." (PMID 40693457, 2025). "In B-lymphoma cells and murine models, the muting of CREBBP/EP300 in tumor cells resulted in polarization of TAMs towards the M2 phenotype by activating the NOTCH signaling pathway and downstream CCL2/CSF1 axis." (PMID 40216772, 2025). "Early studies suggest that disrupting EP300-mediated transcription can reactivate silenced tumor suppressors and improve treatment responses, particularly in fusion-positive cases where normal epigenetic control has been compromised." (PMID 41181124, 2025). "In this study, silencing EP300 in HBV‐positive HCC cell lines reduced tumor growth in vitro and in vivo, accompanied by lower HBeAg and HBsAg concentrations and Ki67 positivity." (PMID 40095759, 2025). "Elevated EP300 expression has been identified in HCC tumors, which are associated with larger tumor size, poorer differentiation, and more advanced stages, making EP300 a promising independent prognostic factor." (PMID 40095759, 2025). "We observed that the expression of EP300 at the mRNA level was significantly lower in primary tumor tissues compared to adjacent normal tissues in ccRCC patients based on TCGA data." (PMID 39179546, 2024). "The EP300 alterations potentially promoted ESCC tumours to become more stem-like phenotypes, which leads to immune exclusion, drug resistance and worse clinical outcomes." (PMID 39419971, 2024).